TK1 (thymidine kinase 1)
Diseases named in the same sentence as TK1 in open-access papers (continued):
Sharing a sentence is not in itself a finding about the gene and the disease.
cancer (continued). "Thus, while PS cells and cancer cells share metabolic features such as dependence on glycolysis and altered mitochondrial metabolism, they significantly differ in their regulation of TK2 and TK1." (PMID 40571767, 2025). "Moreover, low concentrations of TK1 are present in all healthy individuals of all ages, thus, TK1 is neither PCa nor cancer specific." (PMID 36982234, 2023). "Strikingly, there are no TK1 inhibitors for the use in cancer described in the literature so far." (PMID 35203388, 2022). "The potential of TK1 and TK2 as anti-cancer targets in combination with other pyrimidines de novo synthesis inhibitors has only been demonstrated in vitro so that further in vivo experiments are required to fully understand the potential effect of TKs in cancer." (PMID 35203388, 2022). "Finally, coherent and high gene expression of SLC29A2, TK1 and HPRT1 was observed in the three cell lines considered, according to CCLE (Cancer Cell Line Encyclopedia), which enable alternative salvage pathways for purine and pyrimidine synthesis through thymidine and hypoxanthine, respectively." (PMID 35286311, 2022). "Based on the results above, we hypothesized that dTTP, the product of TK1, promotes cancer growth independent of role for TK1 as a regulator of DNA synthesis and repair." (PMID 31589613, 2019). "We also observe that normal cancer adjacent tissue is negative for TK1." (PMID 30214377, 2018). "We found that the DNA methylation level of TK1 in cancer tissues was markedly lower than that in non-tumorous tissues, which may suggests that low TK1 promoter methylation levels are due to the overexpression of TK1 in PCa." (PMID 36035114, 2022). "Thus, the existing antibodies for TK1, may not be sufficient to detect some of the complex TK1 forms that exist in cancer patients." (PMID 32317865, 2020). "Therefore, after normal cell division, the expression level of TK1 is low, while in malignant tumors, abnormal cell proliferation increases and the negative feedback mechanism is disordered, and a large number of TK1 is released into the blood, resulting in an obvious increase in serum TK1 level." (PMID 32202305, 2020). "However, we could not rule out the possibility that serum TK1 activity is reduced only in CDK4/6-dependent cancer cells." (PMID 29162134, 2017). "Although no direct evidence links TK1 and glycosylation in CRC, both are important for cellular functioning and cancer progression." (PMID 40699738, 2025). "This pattern suggests that the cellular TK1 level might not be the main determinant of VACV and OVV replication for all cancer cell lines." (PMID 31963415, 2020). "However, the precise role that TK1 plays in LUAD and other cancer types, as well as its mechanisms-of-action, are still not fully understood." (PMID 31589613, 2019).
infection (9 papers, 2011 to 2025). The state of being infected such as from the introduction of a foreign agent such as serum, vaccine, antigenic substance or organism. "In addition, D39 infection down-regulated expression of the S phase-specific cell cycle thymidine kinase 1 (TK1) gene and the ACTB gene (~4-fold) encoding β-actin and the ADP-ribosylating factor ARF4 gene (~4-fold)." (PMID 26566142, 2015). "In agreement with the RNA-seq results, RRM2, CTPS1, and TK1 were significantly expressed after infection with swH1N1 relative to the pigs infected with huH1N1." (PMID 39247193, 2024). "The prevalence of up-regulated kinase genes highlights a prominent activation of intracellular signaling processes in late-stage infection (Aurka, Aurkb, Cdk1, Tk1, Plk1, Pbk, and Melk) in this article." (PMID 38107402, 2023). "RRM2, CTPS1, and TK1 were highly expressed after infection with swH1N1 compared to huH1N1." (PMID 39247193, 2024). "Infection and inflammation marked by increased TK1 levels have also been shown in canine subjects." (PMID 33292474, 2020). "Of the top 10 transcripts upregulated at peak HIV-1 viral load, the majority (6 out of 10) were related to cell cycle and cell division including RRM2, MYBL2, CDK1, UBE2C, CDC45, and TK1 with 8 to 15-fold increased expression compared to the pre-infection samples." (PMID 31937782, 2020). "Despite no known diseases caused by TK1 deficiency, levels of the enzyme in serum are connected to infection and inflammation." (PMID 33292474, 2020). "As TK1 is a general proliferation marker, several non-malignant conditions like infection, inflammation, autoimmune disorders and benign tissue proliferations might also cause mildly elevated TK1 levels." (PMID 24621590, 2014). "Genes involved in pyrimidine metabolism (RRM2, CTPS1, TK1, NME1, NME2, and UCK2) were induced after infection with swH1N1 compared to huH1N1." (PMID 39247193, 2024). "At 5 days post-infection, viral yields were reduced by at least 10,000-fold in cells expressing SCP1, whereas no significant reduction was observed in cells expressing SCP2 or TK1." (PMID 23966856, 2013).
hematological malignancies (8 papers, 2015 to 2024). "Serum TK1 enzyme activity is a clinically valuable biomarker, and the management of hematological malignancies has been particularly well-studied." (PMID 39006942, 2024). "A set of five serum samples from patients with hematological malignancies were stored at -20°C for a period of 8 weeks, serum TK1 protein levels in these sera were determined with AroCell TK 210 ELISA on day 0 and after 1 week, 2 weeks, 4 weeks, and 8 weeks." (PMID 36201558, 2022). "Another set of four serum samples from patients with hematological malignancies were stored at -80°C for a period of 12 months and TK1 protein levels were analyzed in the sera at regular intervals day 0, and after 1, 2, 4, 8 and 12 months." (PMID 36201558, 2022). "The TK1 protein levels in sera from patients with different hematological malignancies (n = 100: range 0.2 to 48.5 ng/mL, mean±SD = 3.05±8.65 ng/mL; Median = 0.48) were significantly higher compared with blood donors (P<0.0001)." (PMID 36201558, 2022). "In hematological malignancies comparative ROC curve analysis showed that the TK 210 ELISA (sensitivity = 62%) had similar sensitivity to the TK1 activity assay (sensitivity = 59%) at a specificity of 98%." (PMID 36201558, 2022). "In veterinary medicine, serum TK1 have been evaluated as biomarker for diagnosis and prognosis primarily in canines with hematological malignancies." (PMID 34579716, 2021). "Sensitive serum TK1 activity assays have been used for monitoring and prognosis of hematological malignancies in both humans and dogs." (PMID 26366881, 2015). "Interestingly, membrane TK1 seems to be found in monomeric and dimer form similar to membrane TK1 found in hematological malignancies, which suggest kinase enzymatic activity." (PMID 30214377, 2018).
adenocarcinoma (5 papers, 2016 to 2024). A common cancer characterized by the presence of malignant glandular cells. "However, quantitative differences in the expression of Tk1, Top2a, Hmgb2, Rrm2, Kpna2, and H1fx were observed and were found to be strongly up-regulated in small-sized adenocarcinomas." (PMID 27602772, 2016).
haematopoietic tumours (1 paper, 2022). "Thus, TK1 shows good values in terms of diagnostic, prognostic and follow‐up performance in canine haematopoietic tumours, and therefore seems to be a good candidate as a biomarker in this field, despite a certain lack of specificity of this enzyme for other neoplastic pathologies." (PMID 35815441, 2022).
TK1 also shares sentences with these, for which no sentence is quoted: adrenocortical carcinoma (4 papers); acute myeloid leukemia (3); benign tumors (3); Burkitt lymphoma (2); diabetes (2); promyelocytic leukemia (2); rectal cancer (2); small cell lung carcinoma (2); uterine corpus endometrial carcinoma (2); acute T cell leukemia (1); aneurysm (1); asthma (1); bacterial infection (1); benign breast disease (1); cervical squamous cell carcinoma (1); chronic lymphocytic leukemia (1); colorectal (1); dilated cardiomyopathy (1); endocervical adenocarcinoma (1); esophageal cancer (1); histiocytic sarcoma (1); Hodgkins lymphoma (1); Hypertension (1); in situ carcinoma (1); infectious disease (1); kidney cancer (1); liver disease (1); lung squamous cell carcinoma (1); lymphoid neoplasm (1); malaria (1).
A further 18 diseases each share a sentence with TK1 in 1 paper.